ALB (albumin)
Diseases named in the same sentence as ALB in open-access papers (continued):
Sharing a sentence is not in itself a finding about the gene and the disease.
gastric cancer (continued). "Lower albumin levels were associated with NY‐ESO‐1 positivity, possibly because nutritional status deteriorates as gastric cancer progresses." (PMID 38455491, 2024). "We evaluated the noninferiority of non-H1RA (dexamethasone [DEX] alone) premedication to H1RA (plus DEX) premedication in terms of IRRs in patients with gastric cancer receiving RAM plus nanoparticle albumin-bound paclitaxel (nab-PTX)." (PMID 39370483, 2024). "Poor survival was observed in gastric cancer patients with lower levels of BMI, albumin, and triglyceride." (PMID 37447236, 2023). "The present study showed that CRP-increase is associated with higher PS, LDH, and NLR and lower haemoglobin and albumin in the gastric cancer cohort, and higher NLR and lower haemoglobin and albumin in the oesophageal cancer cohort." (PMID 39516365, 2023). "In this study, using Kaplan–Meier to assess, and the results were consistent with previous studies: preoperative high CRP level or low albumin level were both indicators of poor prognosis in patients with gastric cancer." (PMID 37735699, 2023). "Albumin has also been demonstrated as a prognostic factor in gastric cancer, revealing that patients with higher levels of albumin had better prognosis than those with lower levels of albumin." (PMID 36980740, 2023). "The search strategy included the following keywords: "Nanoparticle albumin-bound paclitaxel," "solvent-based paclitaxel," and "advanced gastric cancer," along with their synonyms and medical subject heading (MeSH) terms." (PMID 37575705, 2023). "The C-reactive protein-to-serum albumin ratio (CAR) is an inflammation-based prognostic marker in gastric cancer." (PMID 37373912, 2023). "The role of postoperative of the ratio of c-reactive protein to albumin (CRP/Alb ratio) in the prognosis of gastric cancer is rarely evaluated." (PMID 37735699, 2023). "Among them, HALP score, calculated as Hemoglobin (g/L) × Albumin (g/L) × Lymphocyte (/L)/Platelet (/L), was reported to be related to survival in gastric cancer, colorectal cancer, bladder cancer, and renal cancer patients." (PMID 36980740, 2023). "A significant difference was observed in the nutritional status, as patients with advanced gastric cancers that were suited only for a palliative approach presented lower albumin and total protein levels." (PMID 37046579, 2023). "We assessed the following parameters: body mass index, stage of gastric cancer, C-reactive protein, total lymphocyte count, albumin, and prognostic nutritional index." (PMID 37262024, 2023). "At present, among the new chemotherapy drugs in clinical trials for gastric cancer, albumin paclitaxel (Nab-PTX) and lobaplatin (LBP) have broad application prospects." (PMID 35719323, 2022). "Serum albumin is one of the most important indicators to assess the preoperative nutritional status of gastric cancer patients." (PMID 35198443, 2022). "The relationship between lower serum albumin level and poor prognosis has been reported in various types of cancer including gastric cancer." (PMID 35413824, 2022). "The fibrinogen–ALB ratio effectively and independently predicts the tumor burden and long-term prognosis in patients with gastric cancer." (PMID 36428725, 2022). "After TPN support, Hb, PAB, and ALB in the gastric cancer group were significantly higher than those in the colorectal cancer group on the 7th day after operation." (PMID 35813422, 2022). "The results showed that after EEN support, Hb, TRF, PAB, and ALB in the gastric cancer group were significantly higher than those in the colorectal cancer group at 7 days after operation." (PMID 35813422, 2022). "Recently, adjuvant albumin-bound paclitaxel was also planned to be tested in Chinese gastric cancer patients." (PMID 34507562, 2021). "Studies have shown that ALB was related to the prognosis of various malignant tumors, such as gastric cancer, colon cancer, liver cancer, and glioblastoma." (PMID 34840628, 2021).
gastric cancer (continued). "ALB has been shown to be a prognostic marker in gastric cancer and pancreatic cancer, and the role of albumin as a marker of inflammation has been underscored by recent research in malignancy." (PMID 34221991, 2021). "This multicenter phase III study evaluates the safety and efficacy of nanoparticle albumin-bound paclitaxel (nab-paclitaxel) combined with S-1 in patients with stage III gastric cancer after D2 radical resection." (PMID 33435909, 2021). "The prognostic nutritional index (PNI), which is based on serum albumin and absolute peripheral lymphocyte count, was proved to be a predictive factor for postoperative complication and poor prognosis factor in gastric cancer patients." (PMID 32426291, 2020). "Most patients with advanced tumours, including those with gastric cancer, show decreased albumin levels." (PMID 32184816, 2020). "Recent lines of evidence have identified ALB as an independent prognostic indicator in various malignant tumors, including lung, breast, and gastric cancers." (PMID 32517802, 2020). "This study investigated the prognostic value of the preoperative fibrinogen/albumin ratio (FAR)-systemic inflammation response index (SIRI) score in resectable gastric cancer (rGC)." (PMID 32184816, 2020). "Covariates influencing CL were baseline body weight, aspartate aminotransferase, albumin, gastric cancer, and the presence of liver metastases." (PMID 30467591, 2019). "A risk score system has also been reported for preoperative prediction of the TNM stage of gastric cancer based on four factors: serum albumin, tumor size, and the T and N categories determined by helical computed tomography." (PMID 30849974, 2019). "Diagnosis of gastric cancer cannot be made by means of CT imaging, age, Hb, and albumin values alone." (PMID 31827513, 2019). "Several studies have found that low serum albumin level was an independent prognostic factor for worse outcomes in patients with gastric cancer." (PMID 30116261, 2018). "NLR is one among a spectrum of seven inflammation-based prognostic biomarkers associated with poor survival in gastric cancer, including CRP, albumin, Glasgow prognostic score, platelet-lymphocyte ratio, neutrophil-platelet score and lymphocyte-monocyte ratio." (PMID 29949048, 2018). "Serum albumin (ALB) can indicate the nutritional status, which is an independent prognostic factor for many cancers, including pancreatic carcinoma, gastric carcinoma, nasopharyngeal carcinoma, bladder cancer, and malignant pleural mesothelioma." (PMID 29506546, 2018). "Our findings strongly suggest that low serum albumin levels are a prognostic indicator of poor outcome in gastric cancer patients, which is consistent with previous findings for other malignancies." (PMID 28476041, 2017). "The LysoPS level was higher in the gastric cancer group, even after adjustments to the ALB level, while the PS-PLA1 level, which is a LysoPS-producing enzyme, was not modulated." (PMID 28143894, 2017). "Our nomogram also confirmed the prognostic significance of TBIL and albumin in gastric cancer patients." (PMID 28476041, 2017). "Liu etal. reported that serum albumin was an independent prognostic factor for worse outcomes in 1320 gastric cancer patients after curative resection." (PMID 28476041, 2017). "The purpose of this study was to evaluate the prognostic value of C-reactive protein/albumin ratio in patients with gastric cancer." (PMID 29065877, 2017). "To further assess the predictive ability of TBIL and albumin in gastric cancer patients, we used a nomogram based on the results of the univariate analyses to predict 5-year overall survival rates." (PMID 28476041, 2017). "Regarding glycero-LysoPLs other than LysoPA and LysoPS, we observed that the LysoPI and LysoPG levels were more than twice as high as those in the gastric cancer group and that the LysoPG level remained higher even after adjustment according to the ALB level." (PMID 28143894, 2017).
gastric cancer (continued). "In a separate study of 320 gastric cancer patients, Liu etal. found that preoperative albumin, BMI, and triglyceride levels were more accurate for predicting survival than the TNM system." (PMID 28476041, 2017). "Here, we examined the predictive value of serum bilirubin and albumin levels in 778 gastric cancer patients from a single hospital in China who were divided among prospective training and retrospective validation cohorts." (PMID 28476041, 2017). "Albumin is one of the independent prognostic factors for overall survival in other cancers such as pancreatic cancer and gastric cancer." (PMID 27846279, 2016). "Many recent studies have shown that the levels of systemic inflammatory markers such as C-reactive protein, albumin, fibrinogen, and circulating cellular components are useful prognostic markers for gastric cancer." (PMID 26075713, 2015). "It has been suggested that NLR (calculated as neutrophil count divided by lymphocyte count), CRP level, and albumin level reflect host-response factors in various solid tumors including gastric cancer." (PMID 24906485, 2014). "We investigated the effects of NVP-BEZ235 (BEZ235), a novel dual PI3K/mTOR inhibitor, alone and in combination with nanoparticle albumin-bound (nab)-paclitaxel in experimental gastric cancer." (PMID 24042258, 2013). "TRAF6 was significantly upregulated in muscle of gastric cancer compared with the control muscles, Overexpression of TRAF6 in muscle of gastric cancer were associated with TNM stage, the level of serum albumin and percent of weight loss." (PMID 23013936, 2012). "Overexpression of TRAF6 in muscles of gastric cancer were associated with TNM stage, level of serum albumin and percent of weight loss (P > 0.05)." (PMID 23013936, 2012). "Over expression of TRAF6 in muscles of gastric cancer were associated with TNM stage, level of serum albumin and percent of weight loss." (PMID 23013936, 2012). "This study (TACTIC GC-01) aimed to evaluate the efficacy and safety of fruquintinib combined with albumin-bound paclitaxel as a second-line treatment for advanced gastric cancer (GC) following progression on programmed cell death protein 1 (PD-1) inhibitor-based therapy." (PMID 41449829, 2025). "Furthermore, preoperative albumin levels have also been identified as a prognostic indicator in gastric cancer patients, with low albumin being the most accurate predictor of short-term prognosis." (PMID 40443682, 2025). "We found that prealbumin could more clearly distinguish patients with poorer long-term survival in patients with gastric cancer after radical gastrectomy than albumin." (PMID 39594844, 2024). "Likewise, low serum albumin has been linked to poor prognosis and mortality, and low CEA levels were found to be a risk factor for poor prognosis in cases of gastric cancer." (PMID 38792528, 2024). "The combination of serum albumin and C-reactive protein (CRP) is a useful risk factor for postoperative complications and a prognostic factor postoperatively for long-term survival in patients with gastric cancer." (PMID 39594844, 2024). "Albumin is an important predictor of short-term complications after gastric cancer surgery." (PMID 37901305, 2023). "In addition, FAR was reported to be a valuable marker for predicting long-term adverse prognosis in patients with gastric cancer treated with first-line chemotherapy, and its prognostic value was superior to that of fibrinogen or albumin alone." (PMID 36755341, 2023). "Also, several studies have similar conclusion, low preoperative albumin level plays an important role in judging the prognosis of patients with gastric cancer and can provide information to guide clinical practice." (PMID 37007142, 2023). "Meanwhile, we also analyzed the relationship between postoperative CRP or albumin and the long-term survival of patients with gastric cancer, and we also found that patients with high postoperative CRP level or low postoperative albumin level had shorter survival." (PMID 37735699, 2023).
gastric cancer (continued). "In this study, we found that decreased ALB, an essential prognostic bio-inflammatory marker that responds to nutritional and inflammatory status as well as its antioxidant function, had connection to shorter OS in gastric cancer patients." (PMID 37546387, 2023). "Multiple nutritional assessment systems, including Naples Prognostic Score (NPS), Nutritional Risk Screening (NRS), body mass index (BMI), albumin (ALB), and prognostic nutritional index (PNI), have emerged with the aim of detecting and predicting the clinical outcomes of gastric cancer patients." (PMID 35308215, 2022). "The GNRI can be easily calculated using albumin and BMI and may be useful as a prognostic indicator for gastric cancer in the elderly." (PMID 35549906, 2022). "ETS was associated with maintaining HRQOL in an exploratory analysis of the phase III ABSOLUTE trial that assessed the treatment efficacy of nanoparticle albumin-bound paclitaxel vs. solvent-based paclitaxel in second-line chemotherapy for advanced gastric cancer." (PMID 35765021, 2022). "ALB is widely known as a prognostic indicator of gastric cancer." (PMID 34457006, 2021). "Moreover, a scoring system named Glasgow prognostic score based on inflammation (CRP and ALB) has been validated as versatile in predicting progress for gastric cancer." (PMID 33789664, 2021). "Furthermore, decreased pre-albumin levels are also frequently observed in gastric cancer patients and are correlated with unfavorable survival." (PMID 31772657, 2019). "Regarding the LysoPE species, the levels of 16:0, 18:0, and 22:6 LysoPE were higher in the ascites from the gastric cancer group before adjustment, while the levels of 18:0 and 18:2 LysoPE were lower in the gastric cancer group after adjustment according to the ALB level." (PMID 28143894, 2017). "In this study, we examined whether serum bilirubin and albumin levels were predictive of survival outcomes in gastric cancer patients." (PMID 28476041, 2017). "Taken together, the reduction in weight loss and the smaller decrease in BMI as well as the increases in TP, albumin, and Hb levels after the surgical treatment of gastric cancer indicate that the early administration of an elemental diet improves nutritional status." (PMID 27756322, 2016). "Current clinical research is primarily focused on developing new drugs, such as albumin-bound docetaxel, and studying the efficacy and safety of nab-paclitaxel-based monotherapy or combination therapy as a first- or second-line treatment for advanced gastric cancer." (PMID 39070787, 2024). "The result suggests that preoperative serum albumin and platelet levels in patients with gastric cancer may be valuable predictors, and some studies have even discussed the association of these indicators with short-term postoperative complications in patients." (PMID 35198443, 2022). "The high PLR in gastric cancer patients with mucinous component was connected with larger tumor size, advanced tumor invasion, lymph node metastasis, and advanced TNM stage in our study, but it was also associated with a low hemoglobin level, low albumin level, and high NLR." (PMID 33997045, 2021). "Multivariate analysis showed that gender, age, neutrophil lymphocyte ratio, hemoglobin, albumin, carcinoembryonic antigen (CEA), carbohydrate antigen 125 (CA125) and carbohydrate antigen 199 (CA199) were independent characteristics associated with gastric cancer." (PMID 33382829, 2020). "Therefore, we proposed that a cumulative score based on preoperative fibrinogen in combination with pre-albumin (FP score) might provide more accuracy in predicting long-term survival for resectable gastric cancer patients." (PMID 31772657, 2019). "Therefore, it was hypothesized that in combination with fibrinogen, pre-albumin might provide more accuracy in predicting long-term survival in gastric cancer patients." (PMID 31772657, 2019).
gastric cancer (continued). "In this study, we confirmed the prognostic significance of serum bilirubin and albumin levels and, to our knowledge, demonstrated for the first time that elevated pre-treatment levels of these factors were positive prognostic factors for survival in gastric cancer." (PMID 28476041, 2017). "For example, only pretreatment serum bilirubin and albumin levels were included in the present analyses, and it is possible that dynamic changes in serum bilirubin and albumin levels during the course of treatment might also influence outcomes in gastric cancer patients." (PMID 28476041, 2017). "Thoracic and gastric cancer patients: Systematic review and meta-analysis identified EEN as significantly increasing serum albumin and prealbumin levels, along with immune markers CD3 + and CD4 + lymphocytes." (PMID 41393937, 2025). "In additions, hemoglobin, albumin, lymphocyte, and platelet (HALP) scores showed superior predictive value than TNM staging alone in these gastric cancer patients." (PMID 38982136, 2024). "Several inflammation markers have been used to assess the prognosis of gastric cancer, including mGPS, PLR, CRP/Albumin, and HALP." (PMID 38792528, 2024). "When compared to its components (LMR and albumin) and the original SIS, mSIS proved to be a more accurate predictor of OS in patients with gastric cancer." (PMID 39767217, 2024). "PPI analysis revealed five important proteins, such as ALB, BCL-2, NF-κB, HIF1A, and IL6, from 44 target proteins of gastric cancer according to statistical significance." (PMID 39816318, 2024). "In many studies evaluating patients with advanced gastric cancer who underwent surgery, it has been emphasized that the CRP/albumin level is an important factor in predicting prognosis and mortality." (PMID 38792528, 2024). "In this study, the importance of CRP/albumin ratio and CEA/albumin ratio in the prediction of neoadjuvant treatment response in gastric cancer patients was evaluated." (PMID 38792528, 2024). "In the current research, we established a comprehensive score, IOSS, based on ALB (albumin), DBIL (direct bilirubin), and BUN (blood urea nitrogen), to predict the prognosis of stage III gastric cancer." (PMID 37334172, 2023). "Nutritional markers such as albumin (ALB), prealbumin (PALB), and body mass index (BMI) have been found to be independent prognostic factors for gastric cancer." (PMID 37361569, 2023). "HALP is calculated as follows: hemoglobin (g/L) × Albumin (g/L) × Lymphocytes (/L)/Platelets (/L), and it was first proposed by Chen in 2015, who reported HALP to be a stand-alone predictor of gastric cancer." (PMID 37809958, 2023). "For example, modified SIS that incorporated serum albumin and LMR was proposed as a useful prognostic tool for postsurgical survival in patients with gastric cancer." (PMID 36028993, 2022). "Mean platelet volume (MPV) was analyzed statistically to find a prognostic relationship between monocyte/lymphocyte ratio, platelet distribution volume (PDW), MPV/platelet, c-reactive protein/albumin ratio (CAR), and gastric cancer." (PMID 35547460, 2022). "In advanced gastric cancer, the albumin-globulin ratio (AGR: albumin/total protein—albumin) is an independent prognostic factor for OS and PFS." (PMID 32347434, 2020). "In the human gastric cancer MKN45 xenograft NOD/SCID mouse model, DC101 monotherapy exerted antitumor effects, and combination treatment with nanoparticle albumin-bound paclitaxel (nab-PTX) improved DC101 efficacy." (PMID 33333866, 2020). "In summary, in this study of 778 gastric cancer patients, we found that a nomogram based on serum TBIL and albumin levels was more accurate than the TNM staging system in predicting survival." (PMID 28476041, 2017). "Previous studies have shown that serum albumin, CRP, TNM stage, serum globulin HER-2, CA72-4, and GPS were associated with OS in GC, and they could also predict prognostic factors for survival in gastric cancer." (PMID 27294917, 2016).